PUM1 (pumilio RNA binding family member 1)
Diseases named in the same sentence as PUM1 in open-access papers (continued):
Sharing a sentence is not in itself a finding about the gene and the disease.
cancer (continued). "This review describes PUM1 and PUM2 ribonucleoprotein networks and highlights the mechanisms underlying the regulatory role of PUM proteins and, most importantly, the emerging impact of PUM dysregulation in cancer." (PMID 33401540, 2021). "Furthermore, after network analysis, EPRS, HNRNPA2B1, BPTF, LRRK1, and PUM1 were demonstrated to have a broad correlation with cancers." (PMID 32300588, 2020). "Genes associated with cancer stem cells and EMT markers could be optimally analyzed by normalizing them with GAPDH and PUM1 as housekeeping genes." (PMID 33457124, 2020). "PUM1 came into the pair of RGs for 9 out of 12 cancer types." (PMID 30881377, 2019). "We have systematically analyzed the mRNAs associated with the two human Pumilio RNA-binding proteins, PUM1 and PUM2 in HeLa S3 cancer cells, using a method that combines the recovery of endogenous RNP complexes and DNA microarray analysis of the associated mRNAs." (PMID 18776931, 2008). "Hence, PUM1 is a potential therapeutic target for the treatment of this type of cancer." (PMID 31395860, 2019). "KEGG analysis on these 15 mRNAs and 48 proteins as well as on the target genes of PUM1 PAR-CLIP revealed that they are enriched in cell cycle and cancer pathways, etc.." (PMID 35338151, 2022). "To this end we utilized the publicly available transcriptomic expression datasets from healthy and cancer testis samples and compared the correlation between NANOS3, PUM1, FOXM1, and the model cell cycle targets." (PMID 35743036, 2022). "Consistent with tumorigenic defects in Pum1−/− and Pum2−/− HCT116 cells, PUM proteins appear to regulate the expression of cancer-related genes to promote CRC growth." (PMID 35338151, 2022). "KEGG pathway analyses of the changed mRNAs and proteins in Pum1−/− and Pum2−/− HCT116 cells revealed that cancer-related genes were enriched." (PMID 35338151, 2022). "IPO8, PUM1 and HNRNPL were among the three most stable genes for our set of cancer cell lines and also for all cell lines investigated." (PMID 34593877, 2021). "The accumulated data show that the expression levels of PUM1 and PUM2 are significantly altered in 17 types of cancer tissues." (PMID 33401540, 2021). "In conclusion, we propose the use of IPO8, PUM1, HNRNPL, SNW1 and CNOT4 as reference genes in studies comparing gene expression between different cancer and/or normal cell lines." (PMID 34593877, 2021). "Taking advantage of the Cancer Genome Atlas database, we analyzed RNA expression levels of PUM1 and PUM2 from human cancer samples and compared them to PUM expression in healthy tissues collected within the Genotype-Tissue Expression (GTEx) project." (PMID 33401540, 2021). "We found that the majority of those PUM1- and PUM2-regulated targets are involved in cancer (16 among 19), including 10 in cancer of the male or female reproductive system." (PMID 32316190, 2020). "While PUM1 and BAZ2A have, to our knowledge, not been implicated for the matching cancer types, they have been shown to be potential drivers in other cancers." (PMID 39010058, 2024). "In this type of cancer, even though the level of PUM1 or PUM2 protein itself did not change significantly, the level of the miRNAs (miR-503, miR125b) synergizing with PUM proteins was decreased significantly, which allowed oncogenesis." (PMID 35338151, 2022). "This review summarizes the dysregulation of PUM1 and PUM2 expression in several cancer tissues." (PMID 33401540, 2021). "Notably, in the majority of cancer tissues, PUM2 RNA expression was considerably higher than PUM1 expression." (PMID 33401540, 2021).
cancer (continued). "The findings concerning PUM1 and PUM2 mRNA targets and their functional relations in TCam-2 cells are of interest and should be validated in patients suffering from testis germ cell tumors and several types of cancer affecting other human tissues." (PMID 33401540, 2021).
tumor (26 papers, 2007 to 2025). "Activation of the PERK/eIF2/ATF4 signaling pathway has also been implicated in PUM1-mediated tumor progression in pancreatic adenocarcinoma cells." (PMID 37624174, 2023). "High PUM1 expression correlated significantly with aggressive features of BC, including tumor grade III (p < 0.001), ER− status (p = 0.003), PR− status (p = 0.002), and Ki-67 positive (p = 0.001)." (PMID 41155797, 2025). "By driving immune suppression and hindering CD8+ T cell-mediated anti-tumor responses, PUM1 plays a pivotal role in fostering a tumor-promoting microenvironment." (PMID 40764998, 2025). "Correlations between PUM1 expression and patients’ clinicopathological characteristics (e.g., age, tumor grade, tumor size, and outcome) were assessed." (PMID 41155797, 2025). "Circ_PUM1 high expression promotes proliferation, metastasis, and invasion of EC cells, and the knockdown of circ_PUM1 reduces tumor growth." (PMID 41283360, 2025). "In summary, our results reveal a novel PUM1–DEPTOR–Akt axis that is critical to cause metabolic reprogramming and tumor progression in GC." (PMID 37469018, 2023). "Altogether, these data proved that PUM1 was critical for tumor invasion, metastasis, and peritoneal dissemination of GC." (PMID 37469018, 2023). "When the tumor volume reached ≈150 mm3, siRNA targeting PUM1 or siControl was injected intratumorally every 3 days." (PMID 37469018, 2023). "IHC staining of the tumor sections showed that knockdown of PUM1 significantly reduced the expression of Ki67, indicated reduced proliferation ability." (PMID 37469018, 2023). "Among the seven cell types, PUM1 was mainly expressed in epithelial cell, which was mainly composed of tumor cells." (PMID 37469018, 2023). "Together, these data provided support for the model suggesting that PUM1 positively regulates DEPTOR in a clinical context as a tumor promoter." (PMID 37469018, 2023). "In contrast, injection of nanoparticles loaded with anti-Pum1 siRNA (siPum1@MSN) or anti-Pum2 siRNA (siPum2@MSN) dramatically inhibited tumor growth." (PMID 35338151, 2022). "Pumilio-1 (PUM1) is an RNA-binding pumilio protein with a dramatically increased expression level in various tumor tissues." (PMID 36358919, 2022). "PUM1 stimulates tumor cell proliferation, motility, and colony formation in colon cancer, and is required to regulate tumor spherification." (PMID 36358919, 2022). "HEC‐1B cells with circ_PUM1 knockdown were injected subcutaneously into nude mice, and the tumour volume was significantly smaller than that of the control group at the same time‐point." (PMID 32073729, 2020). "The tumor growth curve also revealed that PUM1 knockdown inhibited the growth of subcutaneous tumors." (PMID 31395860, 2019). "Our results showed that PUM1 knockdown can inhibit the growth of subcutaneous xenograft tumor and decrease the number of metastatic foci and Ki67-positive cells in the lung tissues of a lung metastasis mice model." (PMID 31395860, 2019). "After growth factor stimulation, PUM1 binds to 3'-UTR of CDKN1B/p27 tumor suppressor, inhibits its expression and promotes a rapid entry to the cell cycle." (PMID 30881377, 2019). "In the RNA-seq data, high PUM1 expression was significantly associated with young age (p = 0.0074), negative lymph nodes (p = 0.0034), tumor grade 2 (p < 0.0001), ER+ (p = 0.0084), PR+ (p < 0.0001), and HER2− (p < 0.0001)." (PMID 41155797, 2025). "This study revealed that high PUM1 expression was significantly associated with young age, negative lymph nodes, tumor grade, and the normal and basal-like molecular subtypes." (PMID 41155797, 2025). "In the DNA microarray data, high PUM1 expression was significantly associated with young age, negative lymph nodes, tumor grade 2 (all p < 0.0001), ER− (p = 0.0084), PR+ (p = 0.0438), and HER2− (p < 0.0001)." (PMID 41155797, 2025).
tumor (continued). "Circ_PUM1 (circ_0000043) high expression promotes proliferation, metastasis, and invasion of EC cells; on the contrary, the knockdown of circ_PUM1 is followed by a reduction in tumor growth." (PMID 41283360, 2025). "However, no study has yet examined the prognostic and predictive value of PUM1 in invasive BC and its correlation with aggressive tumor behavior." (PMID 41155797, 2025). "In vitro and in vivo experiments provided further evidence that PUM1 could regulate tumor proliferation, metastasis, and glycolytic metabolism." (PMID 37469018, 2023). "Thus, the in vivo results of the present study support that PUM1 knockdown inhibited tumor growth and metastasis in vivo." (PMID 31395860, 2019). "However, the results suggest that those with high PUM1 expression may benefit from chemotherapy if their tumor develops resistance to hormonal therapy." (PMID 41155797, 2025). "Moreover, high PUM1 expression was significantly associated with the aggressive features of BC, including tumor grade III, negative hormonal receptor status (ER−/PR−), and the triple-negative molecular subtype." (PMID 41155797, 2025). "TPL therapy decreased PUM1 expression in PC, activating autophagy to enhance TRAIL sensitivity in tumor cells." (PMID 36358919, 2022). "PUM1 itself, but not PUM2, strongly stimulated apoptosis and moderately slowed down cell cycle progression, suggesting that PUM1, similarly to SPIN3, plays the role of a tumor suppressor in TCam-2 cells." (PMID 33401540, 2021). "To further confirm the role of PUM1 in PDAC cells, we established a subcutaneous xenograft tumor mouse model and a lung metastasis mouse model." (PMID 31395860, 2019). "MicroRNA-411–5p acts as a tumor suppressor by inhibiting PUM1 mRNA translation in non-small cell lung cancer (NSCLC), which indicates that PUM1 also functions as an oncogene in this disease." (PMID 31395860, 2019). "We also found that PUM1 itself strongly stimulated apoptosis and moderately slowed cell cycle progression in TCam-2 cells, suggesting that PUM1, like SPIN3, is a tumor suppressor." (PMID 30197756, 2018). "Tumour tissue and normal tissue group of five candidate reference genes (CASC3, CDKN1B, POLR2A, PUM1 and UBC) were statistically equivalent to within ± 1.5." (PMID 21806841, 2011). "The analysis showed nearly parallel expression to whole-tissue from the same tumor using the 4-group reference genes for ER+ IBC of TBP, RPLP0, PUM1 and ACTB, as observed by a Pearson correlation of 0.992." (PMID 18211679, 2008). "In multivariate Cox regression including tumor grade, ER status, PR status, HER2 status, and Ki-67 status as factors, PUM1 protein expression was shown to be an independent prognostic indicator of unfavorable survival regardless of these factors (HR = 3.816, 95% CI = 1.826–10.984, p = 0.013)." (PMID 41155797, 2025). "The subcutaneous tumor transplantation experiment and abdominal metastasis experiment in mice further confirmed that overexpression of DEPTOR after silencing PUM1 could restore the proliferation and metastasis of cells in vivo." (PMID 37469018, 2023). "The morphology of the small intestine of knockout mice did not change as compared with the control mice before and after AOM/DSS treatment, indicating the difference in tumor burden between the Pum1/2CKO and control mice were not due to any difference in intestinal anatomy." (PMID 35338151, 2022).
neurodevelopmental disorder (4 papers, 2019 to 2024). A behavioral and cognitive disorder with onset during the developmental period that involves impaired or aberrant development of intellectual, motor, or social functions. "A study has demonstrated the importance of PUM1 for human neurological development and function and has described its role in neurodegenerative and neurodevelopmental disorders." (PMID 35656316, 2022).
infection (3 papers, 2014 to 2025). The state of being infected such as from the introduction of a foreign agent such as serum, vaccine, antigenic substance or organism. "The comparable level of virulence between the wildtype and the pum1Δ mutant was likely due to a low level of expression of Pum1 in the wildtype during infection and it is known that mammalian physiological conditions are extremely inhibitory to the filamentation program." (PMID 24901238, 2014). "Specifically, in cluster 2 with the highest viral load, only three genes including PUM1 (Pumilio homolog; BMSK0008893), PLX-4 (plexin homolog; BMSK0010793), and blistered (bs) (ortholog of serum response factor; BMSK0013093) were significantly up-regulated by BmNPV infection." (PMID 41325423, 2025).
psychiatric disorder (1 paper, 2024). A disorder characterized by behavioral and/or psychological abnormalities, often accompanied by physical symptoms. "Taken together, these data clearly show that translational suppression and accumulation of CLDN-5 mRNAs by attenuation of PUM1 expression, loss of cytosolic PUM1 and/or PUMs-containing stress granules in larger vessels can be associated in a subset of psychiatric disorders." (PMID 38898501, 2024). "CLDN-5 expression levels were not related with the duration of psychiatric disorders, but they were negatively correlated with PUM1 levels (spearman r =-0.3831) and positively correlated with PUM2 levels (spearman r = 0.6030)." (PMID 38898501, 2024).
PUM1 also shares sentences with these, for which no sentence is quoted: developmental disability (3 papers); preeclampsia (3); cerebellar ataxia (2); esophageal squamous cell carcinoma (2); multiple myeloma (2); Adult onset (1); Angelman syndrome (1); Asperger syndrome (1); Au-Kline syndrome (1); autism (1); carcinosarcoma (1); cervical cancer (1); Cognitive impairment (1); colon (1); fragile X syndrome (1); glioblastoma (1); hepatocellular carcinoma (1); Intellectual disability (1); leiomyoma (1); leukemia (1); liver fibrosis (1); major depressive disorder (1); Miscarriage (1); myeloid leukemia (1); neuroblastoma (1); neurological diseases (1); pancreatic adenocarcinoma (1); spinocerebellar ataxia type 1 (1); stomach cancers (1); ZTTK syndrome (1).